C3 (complement C3)
Diseases named in the same sentence as C3 in open-access papers (continued):
Sharing a sentence is not in itself a finding about the gene and the disease.
Stroke (continued). "Increased serum levels of C3, C3c, C4, and MBL are all associated with increased stroke severity, and patients who are MBL-sufficient have higher C3 plasma levels and suffer worse stroke outcomes." (PMID 31417544, 2019). "For instance, C3 complement protein can promote damage during the acute stage of a stroke and also promote improved long-term repair in the weeks following the stroke." (PMID 31272467, 2019). "The presence complement molecules including Clq, MBL, C3, C4d, C5a, and C9 has been observed in ischemic brain sites and increased levels of C3, C4d, C5a, and C5b-9 have also been found in the plasma of stroke patients." (PMID 30131754, 2018). "In stroke, the central complement component C3 is predominantly cleaved through the mannose binding lectin (MBL) pathway." (PMID 28700732, 2017). "Compared to healthy volunteers, stroke patients were found to have higher plasma levels of C3a, C3, C4, C5, factor B, and the terminal complement complex." (PMID 26322048, 2015). "Systemic activation of the complement system takes place in connection with an ischemic brain insult and elevated blood levels of C3, C3a, C4d and C5-9b have been found in patients in an early post-stroke phase." (PMID 23977229, 2013). "With regard to the correlation between systemic hsCRP and C3 levels, CE appears to resemble the cryptogenic stroke subtype." (PMID 23977229, 2013). "Our group has previously employed gene-deleted mice in combination with specific pharmacologic inhibitors to identify C3 as the central mediator of complement-induced acute cerebral ischemic injury following reperfused stroke in mice." (PMID 22761695, 2012). "Additionally, C3 knockout mice show reduced infarct volume and improved neurological function post MCAO, highlighting C3 as a promising therapeutic target in stroke." (PMID 41002405, 2025). "Complement C3 plays a multifaceted and temporally dynamic role in stroke." (PMID 41187099, 2025). "In summary, complement C3 exerts phase-specific and cell-type-dependent effects in stroke." (PMID 41187099, 2025). "Clinical studies have demonstrated that plasma C3 levels are elevated in patients with stroke." (PMID 39012667, 2024). "Besides, some experimental studies have shown that IgG exhibits a prominent neuronal protective potential in the treatment of TBI and stroke by removing the C3 complement and downregulating the toll-like receptor of neurons." (PMID 37254196, 2023). "An inhibitor of C3 activation, Crry, targeted to ischemic neurons, prevented phagocytosis of stressed-but-salvageable neurons and synapses in the ischemic penumbra, and improved cognitive function in mouse models of stroke." (PMID 34948237, 2021). "An inhibitor of C3 activation, Crry, prevented phagocytosis of stressed-but-salvageable neurons and synapses in the ischemic penumbra and improved cognitive function in a mouse model of stroke." (PMID 34948237, 2021). "Thus, manipulation of C3-mediated activities after stroke would have to be highly targeted and temporally regulated." (PMID 33239010, 2020). "Evidence suggests that complement C3 is central to stroke pathology in animal models." (PMID 33239010, 2020). "C3 mRNA is also upregulated in sprouting axons 7 days after stroke." (PMID 23936241, 2013). "Activation of complement component C3 produces potent opsonins to tag neurons for phagocytosis, and an inhibitor of C3 activation, Crry, prevented phagocytosis of stressed-but-salvageable neurons in peri-infarct areas, and reduced functional deficits in a mouse model of stroke." (PMID 35216419, 2022). "However, the role of C3 in the pathophysiology and tissue regeneration after ischemic stroke needs to be further investigated, especially in the subacute and chronic phases of stroke." (PMID 31011487, 2019).
Stroke (continued). "First, as several components, such as C1q, C3, and C3aR, are involved in synaptic plasticity and neurogenesis under both normal and stroke conditions, it is imperative to choose more specific and focused complement modulation, which may cause fewer undesired complications." (PMID 31011487, 2019). "Finally, unlike C3 deficiency, targeted complement inhibition did not increase susceptibility to lethal post-stroke infection, an important consideration for stroke patients." (PMID 26714866, 2015). "It has also been shown that targeted complement inhibition with CR2-Crry does not impair host susceptibility to infection, unlike systemic inhibition of C3 deficiency, a potentially important consideration for stroke patients who are at increased risk of infection." (PMID 26322048, 2015). "C3 deficiency and site-targeted complement inhibition with either CR2-Crry (inhibits all pathways) or CR2-fH (inhibits alternative pathway) significantly reduced infarct size, reduced apoptotic cell death, and improved neurological deficit score in the acute phase after stroke." (PMID 26714866, 2015). "In a proteomics stroke study, researchers identified ICAM-2, STXBP5, PLGLA, C3, and IGHV3-64 as candidate biomarkers in blood, yielding a high (75% to 88%) sensitivity for identifying stroke patients." (PMID 40362186, 2025). "To investigate TT1Ct effects on the glial subpopulation in stroke, we first evaluated GFAP and complement component 3 (C3) co-staining after 5 h or 24 h of injury." (PMID 40225562, 2025). "Plasma C3 and C3a levels in 79 CE and 79 SVD stroke patients, sampled within 10 days and at three months after stroke, and age- and sex-matched control subjects from The Sahlgrenska Academy Study on Ischemic Stroke were measured by ELISA." (PMID 23977229, 2013). "In the acute phase after stroke, endothelial activation and leukocyte recruitment into the brain are reduced in mice lacking C3 and C3aR." (PMID 34379293, 2021). "In the SVD but not CE subtype, C3 levels remained elevated also three months after stroke and high plasma C3 levels at this time point showed an association with patient status independently of traditional risk factors." (PMID 23977229, 2013). "At 4 weeks post-stroke, the top 10 gene products in the PPI network were Cd44 (degree = 17), C1qb (degree = 15), Fcgr2b (degree = 14), Spp1 (degree = 12), Cd74 (degree = 12), C4a (degree = 12), C1qa (degree = 12), C3 (degree = 10), Cd14 (degree = 10), and Itgb2 (degree = 10)." (PMID 31888302, 2019). "Application of CVF, C1-inhibitor, C3-inhibition through soluble CR1 or C3-deletion, as well as immunoglobulin treatment, have all shown protective effects in adult stroke animal models, suggesting that complement-targeted therapy could prove effective in neonatal HI and needs further investigation." (PMID 25729383, 2015). "Both C3 expression and caspase-3 activation were reduced with intravenous immunoglobulin (IVIG) treatment, suggesting that IVIG may represent an interventional therapy for stroke." (PMID 26322048, 2015). "Microbiocidal49,50C3 and C4b were initially downregulated at 2 and 5 days but were then persistently upregulated through 70 days, and immunoreactive C3 protein was prominently detected in lesion border astrocytes that interfaced with non-neural lesion core cells in SCI and stroke." (PMID 38907165, 2024).
Arthritis (59 papers, 2007 to 2026). Inflammation of a joint. "Intracellular C3 convertase-independent C3a generation and C3aR activation contribute to homeostatic mTOR activity and T-cell survival, and increased intracellular C3 activation underlies T effector dysregulation in arthritis." (PMID 26787717, 2016). "We found here that C3-deficient K/BxN mice developed arthritis equivalent in severity to C3-sufficient animals." (PMID 23237573, 2012). "Specifically, mice with targeted or naturally occurring mutations in the genes encoding factor B (of the alternative pathway), C3, C5, the C5a receptor (C5aR), and FcRγ were protected from developing serum-transferred arthritis." (PMID 23237573, 2012). "In our patient, ASO titres and C3 levels were normal, ruling out other causes of arthritis." (PMID 40124691, 2025). "Studies using C3−/− and C5−/− mice models have demonstrated that C3-independent C5 activation occurs in some diseases like acute lung injury, LPS-induced fetal loss, and autoantibody-meditated arthritis." (PMID 35087765, 2021). "However, in those diseases mediated by thrombin that have a C3-independent C5 activation, such as acute lung injury, LPS-induced fetal loss, and autoantibody-meditated arthritis, C3−/− mice still had the same disease susceptibility as wild-type mice." (PMID 35087765, 2021). "Indeed, the mice deficient for C3 or factor B were highly resistant to experimental arthritis, indicating that complement activation by both the classical and the alternative pathway acts as a deleterious role in inflammatory." (PMID 31214191, 2019). "Septic arthritis in neutrophil-depleted mice and in C3-deficient mice shows very similar disease patterns, e.g., a higher bacterial load in the kidneys, more severe arthritis, and greater body weight loss, indicating a strong connection between neutrophils and C3 in hematogenous septic arthritis." (PMID 26787717, 2016). "Subgroup analysis showed that plasma levels of BTN3A1 were significantly related to several clinical and laboratory features, such as vasculitis, arthritis, cylindruria, and were significantly correlated with C3, RF expression." (PMID 40959207, 2025). "For instance, C3 activation in synovial fibroblasts induces metabolic changes that prime them for chronic inflammation in arthritis." (PMID 40309766, 2025). "The clinical and immunological characteristics that were statistically associated with positive EULAR/ACR-2019 criteria were renal involvement, arthritis, low C3 and C4 and a positive test for DNA, with all of those important and highly specific to SLE." (PMID 34071275, 2021). "Of the five STGD1 patients who suffered from a rheumatic disorder, two had active arthritis during blood draw and both of these patients had an elevated C3d/C3 ratio." (PMID 34170959, 2021). "In the same sense, circulating C3 appears as an element necessary and sufficient for arthritis induction in this model." (PMID 33451011, 2021). "SLEDAI at time of initial diagnosis prior to start of immunosuppressive therapy was 14, and comprised of arthritis, rash, mucosal ulcers, low complement (C3/C4), increased DNA binding, fever, and leukopenia." (PMID 28555177, 2017). "MMP-12 has been shown to dampen inflammation in arthritis by inactivating complement C3 and degrading neutrophil extracellular traps (NETS)." (PMID 29216931, 2017). "Here we studied the interplay of C3, C5, and activating FcγRs in a model of spontaneous autoantibody-driven arthritis." (PMID 23237573, 2012). "Here, we investigated a possible contribution of C3-independent mechanisms of C5 activation in a mouse model of autoantibody-mediated arthritis." (PMID 23237573, 2012). "Consistent with studies in mice, synovial aspirates from patients with RRV-induced arthritis have been shown to contain increased levels of the C3 cleavage product C3a." (PMID 22457620, 2012).
Arthritis (continued). "In GPI-induced arthritis, IgG and C3 are co-localized on the articular surface of arthritic joints (Tanaka and coworkers, unpublished data)." (PMID 18534002, 2008). "Recent studies identified co-localization of IgG and C3 on the articular surface of joints in GPI-induced arthritis on day 14, and production of anti-GPI antibodies was most vigorous on day 8 (Tanaka and coworkers, unpublished data)." (PMID 18534002, 2008). "Parabionts having C3 only in the circulation remained sensitive to arthritis induction, and the cartilage of these arthritic mice contained deposits of C3." (PMID 17763447, 2007). "In a mouse model wherein the alternative pathway of complement activation is critical to the induction of arthritis by autoantibodies, circulating C3 was necessary and sufficient for arthritis induction." (PMID 17763447, 2007). "Female patients with SLE most commonly develop clinical manifestations like alopecia (60.90%), photosensitivity (60.70%), oral ulcers (51.00%), arthritis (74.20%), malar rash (55.60%),​ discoid lupus (20.40%), and low complement component 3 (C3) activities (51.10%)." (PMID 39677179, 2024). "Notably, synovial fibroblasts were recently shown to drive the local inflammatory tissue priming in preclinical models of arthritis in a C3-dependent manner; the primed fibroblast appeared to upregulate both C3 and CXCL14 mRNA expression." (PMID 38832018, 2024). "The different in vivo models of RA have concordantly shown that mice deficient in complement components and related proteins (C3, factor B, C5 C5aR, and MASP1/3) are protected against the development of arthritis, with a greater protective effect for C5 than C3." (PMID 35242041, 2022). "Performing RNAseq analysis of the megakaryoblastic cell line Meg-01 we could show that C3 regulates gene-expression which may affect their functional role in the disease course of arthritis." (PMID 35880182, 2022). "So which component of the complement system C3 or C5 is important for the development of arthritis?" (PMID 29892280, 2018). "Finally, regardless of the activation route, all of these pathways generate two major potent pro-inflammatory molecules; C3a and C5a, via C3 and C5 convertases, respectively, which play a vital role in the pathogenesis of arthritis." (PMID 29892280, 2018). "A vital role for complement in CIA was first suggested by studies in rats, in which injection of cobra venom factor (CVF), inducing marked activation followed by depletion of complement components, led to a delay in the onset of arthritis until serum C3 levels returned to normal." (PMID 29892280, 2018). "SS-onset SLE were younger and had an increased frequency of arthritis, xerostomia, anticardiolipin antibodies and low levels of C3 and C4 in the serum, perivascular infiltrates in the salivary glands but a lower frequency of interstitial lung disease when compared with SS-only." (PMID 28415674, 2017). "In addition, it has been shown that circulating C3 is necessary and sufficient for arthritis induction." (PMID 27313578, 2016). "All three pathways of the complement system lead to the generation of C3, which has been shown to be indispensable for arthritis induction, thus emphasizing the general importance of complement activation in this model; in contrast, the C3-receptor seems to be dispensable." (PMID 27313578, 2016). "Next, we asked whether opsonization of S. aureus in WT serum prior to inoculation would affect the clinical course of arthritis after hematogenous inoculation in C3−/− mice." (PMID 26787717, 2016). "Circulating C3 is necessary and sufficient for antibody-driven K/BxN serum transfer arthritis." (PMID 25596646, 2015). "Neither C3 nor fB deficiency affects local S. aureus arthritis." (PMID 26787717, 2016).
Arthritis (continued). "In further support of this notion, serum from C3−/− mice failed to opsonize the bacteria, and preincubation of S. aureus with WT serum prior to hematogenous injection was associated with a trend toward milder arthritis in C3−/− mice." (PMID 26787717, 2016). "It correlates with distinct clinical (rash, alopecia, arthritis, Raynaud syndrome) and immunological (anti-Sm/SSA/SSB antibodies, decreased C3/C4, RF positivity) features." (PMID 41495809, 2026). "Similar to therapeutic C3 supplementation in drinking water, C3 FMT, when done at the peak of arthritis, promoted fast resolution compared with transfer of control FM." (PMID 40638239, 2025). "To determine the effect of C3 on arthritis progression and bone marrow progenitor populations in mice, we supplemented CIA mice with C3 with the onset of clinical arthritis scores starting at 21 days post immunization (dpi) in the drinking water." (PMID 35880182, 2022). "The complement system is important in arthritis development in CAIA, and the serum C3 levels were increased by 31 % in CAIA mice compared with controls." (PMID 26209517, 2015). "The development of arthritis in K/BxN serum-transferred mice, a model in which autoantibodies against glucose-6-phosphate isomerase play an important role, is suppressed by the deficiency of factor B, C3, C5 or C5a, but not by C1q or MBP-A, suggesting the involvement of the AP in the pathogenesis." (PMID 26404464, 2015). "Hence, osteoblasts may produce alternative complement factors in a GC-dependent way (e.g. C3, factor B, factor H), and reduction of these osteoblastic alternative complement factors could be responsible for attenuation of arthritis in Col2.3-11β-HSD2-transgenic mice." (PMID 24491163, 2014). "By using T cells isolated from arthritis patients, we demonstrated that increased CTSL-mediated activation of C3 is connected with uncontrolled pathological effector T cell function." (PMID 24315997, 2013). "Reduced levels of complement C3, elevated anti-double-stranded DNA antibody titers, active urine sediment, and other SLE flare manifestations such as rash, arthritis, and hematological abnormalities may support the diagnosis of LN flares." (PMID 37781682, 2023). "Regarding the EULAR/ACR-2019 criteria, statistically significant associations were found between meeting the EULAR/ACR-2019 classification criteria and the presence of low C3 and C4 (p = 0.03), anti-dsDNA (p < 0.01), lupus nephritis III-IV (p < 0.05) and arthritis (p < 0.01)." (PMID 34071275, 2021). "A 60-year-old African American woman was diagnosed with systematic lupus erythematosus (SLE) in December 1999, characterized by malar rash, arthritis, proteinuria, leukopenia, positive ANA (1:640, homogenous and speckled pattern), anti-Smith, anti-RNP, and low C3." (PMID 28203576, 2017). "In contrast, rhCTRP6 failed to treat arthritis in C3−/− mice, suggesting that C3 is involved in the manifestation of CTRP6 action." (PMID 26404464, 2015). "The key finding of this study is that autoantibody-mediated arthritis in K/BxN mice can occur via a C5 activation pathway that requires neither C3 nor activating FcγRs, the two main effector mechanisms of IgG molecules." (PMID 23237573, 2012). "In K/BxN mice, C5-dependent autoantibody-driven arthritis can occur in the genetic absence of both complement C3 and activating FcγRs." (PMID 23237573, 2012). "In short, production of C3 by leukocytes was not required for K/B×N serum-induced arthritis, even with prolonged administration of arthritogenic serum." (PMID 17763447, 2007). "However, other authors have shown that the presence of C3 is not necessary for the development of arthritis in this same model, suggesting that the pathogenesis can largely proceed by complement-independent pathways." (PMID 33451011, 2021). "Mice lacking FH do not develop arthritis due to the lacking of C3 present in the circulation." (PMID 29892280, 2018).
Arthritis (continued). "Hence, the differences between the C3−/− and the fB−/− and WT mice in clinical arthritis and the opsonization capacity of C3−/− versus fB−/− and WT sera are conceivably due to the absence of C3 and not due to lower levels of antibodies specific for S. aureus." (PMID 26787717, 2016). "Importantly, we also detected mRNA for C3 in mouse synovium by both cDNA microarray and quantitative PCR (not shown), though we did not see an increase as arthritis unfolded." (PMID 17763447, 2007). "Furthermore, the transfer of purified GPI-specific autoantibodies from K/BxN mice was able to induce arthritis in DBA/1 mice with features similar (but not identical) to those of human RA, and the deposition of GPI-CIC and activated C3 was found on the articular cartilage surface." (PMID 25889507, 2015).